RCE1 (Ras converting CAAX endopeptidase 1)
Description:
Protease involved in the processing of a variety of prenylated proteins containing the C-terminal CAAX motif, where C is a cysteine modified with an isoprenoid lipid, A is an aliphatic amino acid and X is any C-terminal amino acid. Proteolytically removes the C-terminal three residues of farnesylated and geranylated proteins, leaving the prenylated cysteine as the new C-terminus. Is able to process K-Ras, N-Ras, H-Ras, RAP1B and G-gamma-1.
Synonyms: FACE-2; hRCE1; FACE2; RCE1A; RCE1B
Tractability: Small molecule: a high-quality ligand is known; it belongs to a druggable protein family. Antibody: its Gene Ontology location is reachable by antibodies, with high confidence; UniProt predicts a signal peptide or a membrane-spanning region. PROTAC: UniProt records ubiquitination sites on it; ubiquitination databases record sites on it; a small molecule that binds it is known.
Target class: Protease unclassified; Protease; Enzyme; Protease unclassified U family; Protease unclassified U48 family
Gene: Protein-coding gene on chromosome 11 (66,842,835 to 66,846,552, forward strand). Ensembl gene ENSG00000173653.
Subcellular location: Endoplasmic reticulum membrane
Pathways (Reactome):
Metabolism of proteins: Ub-specific processing proteases
Signal Transduction: RAS processing
Gene Ontology:
Molecular function: endopeptidase activity; exopeptidase activity; cysteine-type endopeptidase activity; metalloendopeptidase activity
Biological process: CAAX-box protein processing; protein prenylation; MAPK cascade; CAAX-box protein maturation
Cellular component: endoplasmic reticulum membrane; membrane; cytosol; plasma membrane
Genetic constraint (gnomAD): Loss-of-function variants: 15 observed, 32.45 expected, observed/expected ratio (o/e) 0.46, 90% interval 0.31 to 0.71. The synonymous counts are far from expectation, so gnomAD's model fits this gene poorly and the ratio says little. Missense variants: 434 observed, 423.72 expected, observed/expected ratio (o/e) 1.02, 90% interval 0.95 to 1.11. Synonymous variants: 261 observed, 187.83 expected, observed/expected ratio (o/e) 1.39, 90% interval 1.25 to 1.54.
Homologues: Orthologues: chimpanzee RCE1 (99% identical), macaque RCE1 (99% identical), pig RCE1 (98% identical), mouse Rce1 (95% identical), guinea pig RCE1 (94% identical), dog RCE1 (87% identical), rat Rce1 (75% identical), zebrafish rce1a (65% identical), rabbit RCE1 (62% identical), tropical clawed frog sart1 (51% identical), Drosophila melanogaster Sras (34% identical), Caenorhabditis elegans fce-2 (26% identical).
Diseases named in the same sentence as RCE1 in open-access papers:
RCE1 is named in the same sentence as 18 diseases in open-access papers, as found by Europe PMC text mining. Sharing a sentence is not in itself a finding about the gene and the disease. The quoted sentences say what the papers report.
prostate carcinoma (2 papers, 2020 to 2024). A carcinoma that arises from epithelial cells of the prostate gland. "RCE1 shows correlation with tumor progression, e.g., overexpression is positively correlated with prostate cancer, and down-regulation predicts poor prognosis in hepatocellular carcinoma." (PMID 39734218, 2024). "Deletion of RCE1 reduced the growth of fibroblasts and skin carcinoma cells, and overexpression of RCE1 was reported to correlate with prostate cancer progression and predict poor prognosis." (PMID 32370292, 2020).
breast carcinoma (1 paper, 2024). "The novel Ras membrane-bound regulator of Ras, Rce1, suggests a promising strategy for targeting Ras in breast cancer, and KPNA2 overexpression significantly enhances the invasion and migration capabilities of breast cancer cells." (PMID 39720180, 2024).
colon cancer (1 paper, 2017). "Although there was a significant difference in the OS and DFS between patients who had different RCE1 expression levels in colon cancer and rectal cancer, the RCE1 expression level had a more significant prognostic value in rectal cancer." (PMID 28615075, 2017). "We further explored the prognostic significance of RCE1 in colon cancer and rectal cancer." (PMID 28615075, 2017).
colorectal cancer (1 paper, 2017). A primary or metastatic malignant neoplasm that affects the colon or rectum. "Despite the lack of direct evidence, our study also provided clues about the function of the RCE1-p38 signaling pathway in colorectal cancer." (PMID 28615075, 2017). "The aim of the study is to investigate expression pattern of RCE1 and its prognosis in colorectal carcinoma (CRC)." (PMID 28615075, 2017). "RCE1 might participate in Ras activation; However, the role of RCE1 genes in colorectal carcinoma has not been explored." (PMID 28615075, 2017).
gout (1 paper, 2024). A condition characterized by painful swelling of the joints, which is caused by deposition of urate crystals. "Ultimately, eight genes were identified as possible drug targets in gout, including three risk genes (ALDH3B1, NRBP1, SUMF1) and three protective genes (FCGR2B, RCE1, SLC7A7)." (PMID 39734218, 2024). "Eight potential therapeutic targets (ALDH3B1, FCGR2B, IL2RB, NRBP1, RCE1, SLC7A7, SUMF1, THBS3) for gout were identified in the discovery cohort using MR analysis." (PMID 39734218, 2024).
lipodystrophy (1 paper, 2022). A congenital or acquired disorder characterized by abnormal loss or redistribution of the adipose tissue in the body. "Rce1 inhibition has raised some toxicity concerns and the selective inhibition of Rce1 remains a difficult task since the inhibition of functionally related Ste24 results in progeria, muscular dystrophy, and lipodystrophy." (PMID 35628237, 2022).
tumor (6 papers, 2017 to 2025). "Although the literature has reported that RCE1 is important for the activation of the Ras oncogene, our results suggested that RCE1 had an anti-tumor role in CRC." (PMID 28615075, 2017). "The data suggested that RCE1 expression, depth of tumor invasion, histological grade and node stage had prognostic value." (PMID 28615075, 2017). "Further study indicated that RCE1 influenced tumor invasion through the p38 pathway." (PMID 28615075, 2017). "Taken together, the outcomes of this study indicate that RCE1 acts as a tumor suppressor in CRC, as its reduced expression may increase CRC cell invasion and independently predict an unsatisfactory prognosis in CRC patients." (PMID 28615075, 2017). "By considering the well-known carcinogenic and tumor-promoting effect of Ras activation, we initially hypothesized that RCE1 might promote CRC development by participating in Ras activation." (PMID 28615075, 2017). "Furthermore, our study also indirectly indicated that RCE1 might exert a tumor suppressing function as a result of increasing levels of phosphorylated p38." (PMID 28615075, 2017). "Our results indicated that the expression level of RCE1 was negatively correlated with the plasma levels of CEA, depth of tumor invasion, node stage and TNM stage (p < 0.05)." (PMID 28615075, 2017). "Our results suggested that RCE1 expression was reduced in CRC tumor tissues compared with adjacent non-tumorous tissues." (PMID 28615075, 2017). "Although it does not offer direct evidence, our finding indirectly proves that RCE1 exerted a tumor suppressor function that was independent of the Ras oncogene." (PMID 28615075, 2017). "From TCGA tumor expression data via GEPIA2, the top 100 genes positively correlated with LRFN4 expression were determined, among which TPX2 (R = 0.36), KIF18B (R = 0.39), RCE1 (R = 0.53), PCNXL3 (R = 0.49), and SAMD1 (R = 0.48) showed significant correlations (P < 0.001)." (PMID 40386777, 2025). "Moreover, RCE1 expression was high in 188 (77.0%) of the adjacent non-tumorous tissues but only in 138 (56.6%) of the tumor tissue samples." (PMID 28615075, 2017).
infection (1 paper, 2020). The state of being infected such as from the introduction of a foreign agent such as serum, vaccine, antigenic substance or organism. "The CPBP family consists of two branches: eukaryotic Rce1 CaaX proteases and prokaryotic abortive infection (abi) proteases." (PMID 33024034, 2020).
RCE1 also shares sentences with these, for which no sentence is quoted: cancer (5 papers); neuroblastoma (3); autoimmune disease (1); bladder carcinoma (1); hepatocellular carcinoma (1); melanoma (1); muscular dystrophy (1); progeria (1); rectal cancer (1); skin carcinoma (1).